PTK6 (protein tyrosine kinase 6)
Diseases named in the same sentence as PTK6 in open-access papers (continued):
Sharing a sentence is not in itself a finding about the gene and the disease.
breast carcinoma (continued). "PTK6 and extracellular signal-regulated kinase 5 (ERK5) mediate Met receptor signaling to promote breast cancer cell migration." (PMID 35562900, 2022). "Specific breast cancer interactions involved, for instance, the focal adhesion, DAP12 and PTK6 signaling pathways." (PMID 33670716, 2021). "For instance, PTK6 interacts and phosphorylates PSF to induce PSF cytoplasmic relocalization and cell cycle arrest in the breast cancer cell line BT-20 via the c-terminal tyrosine residue of PSF and the SH3 domain of PTK612." (PMID 31844057, 2019). "Protein tyrosine kinase 6 (PTK6, or BRK) is aberrantly expressed in breast cancers, and emerging as an oncogene that promotes tumor cell proliferation, migration and evasion." (PMID 29879184, 2018). "Our results are also interesting in light of a previous study showing that PTK6 promotes p38 MAPK activation, subsequent Cyclin D1 expression and migration in the context of heregulin- or EGF-stimulated breast cancer cells." (PMID 26084280, 2015). "We show that PTK6 contributes to both tumor initiation and metastasis in the MMTV-ERBB2 mouse model of breast cancer." (PMID 26247733, 2015). "Breast tumor kinase (BRK), also known as protein tyrosine kinase 6 (PTK6), is a non-receptor tyrosine kinase overexpressed in more that 60% of human breast carcinomas." (PMID 24523872, 2014). "Striking localization of PTK6 P-Y342 at the plasma membrane was detected in IDC, the most common type of breast cancer, as well as in DCIS, the most common non-invasive breast cancer." (PMID 25153721, 2014). "We detected ALT-PTK6 transcripts in all breast cancer cell lines analyzed by semi-quantitative PCR, although the ratio of full length PTK6 to ALT-PTK6 varied from cell line to cell line." (PMID 25153721, 2014). "PTK6 expression was low or undetectable in normal ovary or normal breast epithelium, but it was found in human ovarian tumor cells and in greater than 60% of breast tumors and breast cancer derived cell lines, indicating that overexpression of PTK6 may be related to carcinogenesis." (PMID 23497344, 2013). "Novel functions of STAT5b, a new target for breast tumor kinase/protein tyrosine kinase 6 (Brk/PTK6), have been reported and the involvement of STAT5b in breast cancer cell migration has been demonstrated." (PMID 22485142, 2012). "Although cytoplasmic protein tyrosine kinase 6 (PTK6; breast tumour kinase (BRK)) is overexpressed in up to 86% of breast carcinomas, its physiological role is rather unclear." (PMID 20700126, 2010). "Overexpression of PTK6-mRNA positively correlates with hormone receptor status and HER2/NEU expression in breast cancer specimens." (PMID 17299391, 2007). "PTK6, a non-receptor tyrosine kinase, modulates the pathogenesis of breast and prostate cancers and is recognized as a biomarker of breast cancer prognosis." (PMID 37509364, 2023). "In the current study, Kaplan–Meier survival analysis showed that the OS and DFS of PTK6-positive patients were lower than those PTK6-negative patients in the LNM + group, which also confirmed that PTK6 was associated with poor prognosis of breast cancer." (PMID 37932734, 2023). "When compared with nontumor specimens, the expression of PTK6 was noticeably upregulated in breast cancer samples." (PMID 36405012, 2022). "Because of its established roles in prostate and breast cancer, we explored how PTK6 and SRC are coexpressed in nonmalignant and malignant prostate and breast cancer tissues." (PMID 36228719, 2022). "Finally, we show that PTK6 and SRC are coexpressed in subsets of human prostate and breast cancer cells, and active PTK6 and active SRC colocalize in prostate cancer, supporting a role for PTK6 in promoting SRC activity in cancer." (PMID 36228719, 2022). "PTK6 cooperates with HER2 and Src to regulate EMT in HER2-positive breast cancer cells." (PMID 35562900, 2022). "Furthermore, PTK6 and SRC activation have been correlated with resistance to HER2 inhibitors in breast cancer." (PMID 36228719, 2022).
breast carcinoma (continued). "PTK6 was found to be upregulated in many tumor tissues, including breast cancer, bladder cancer, non-small cell lung cancer, and ovarian cancer, and is associated with adverse outcomes." (PMID 34721517, 2021). "PTK6 (Protein tyrosine kinase six) is a cytoplasmic non-receptor protein kinase thatis highly expressed in tumors such as breast cancer, bladder cancer, lung cancer, and ovarian carcinoma." (PMID 33768004, 2021). "Overall, these findings suggest that the kinase activity of PTK6 does not play a significant role in tumorigenesis, thus providing important evidence against PTK6 kinase as a potential therapeutic target for breast cancer treatment." (PMID 29879184, 2018). "Although PTK6 is highly expressed in ER+ Luminal breast cancers, the role of PTK6 in this subtype has not been elucidated." (PMID 29167821, 2017). "The non-receptor tyrosine kinase, PTK6/BRK, is highly expressed in multiple tumor types, including prostate, ovarian, and breast cancers, and regulates oncogenic phenotypes such as proliferation, migration, and survival." (PMID 29167821, 2017). "This requirement for p38 MAPK activation appears to be conserved between ER+ and HER2+ breast cancer cells; we previously showed that p38 activation is required for apoptosis of lapatinib-resistant HER2+ breast cancer cells in which PTK6 expression was downregulated." (PMID 29167821, 2017). "PTK6 was found to be overexpressed in breast cancer, non-small cell lung cancer, and ovarian cancer." (PMID 27311570, 2016). "Strategies that enhance Bim expression, such as PTK6 inhibition, could therefore be an effective strategy to induce death of TKI-resistant Her2+ breast cancer cells." (PMID 26084280, 2015). "PTK6, a member of a distinct family of non-receptor tyrosine kinases distantly related to Src kinases, is expressed in breast cancers and multiple other cancer types." (PMID 26084280, 2015). "PTK6 also cooperates with HER2 and Src to regulate breast cancer cell survival." (PMID 25748447, 2015). "Disruption of Ptk6 significantly delayed and reduced ERBB2-induced mammary gland tumor formation and metastasis, providing strong rationale for therapeutically targeting PTK6 alone or in combination with other agents in ERBB2/HER2-positive breast cancers." (PMID 26247733, 2015). "Protein tyrosine kinase 6 (PTK6) is a non-receptor tyrosine kinase that is highly expressed in Human Epidermal Growth Factor 2+ (Her2+) breast cancers." (PMID 26084280, 2015). "In the studies of breast cancer cells, PTK6 has been reported to enhance EGF-induced cellular migration, while overexpression of PTK6 was reported to increase cellular invasive potential by inducing epithelial mesenchymal translation (EMT) in prostate cancer cells." (PMID 24788754, 2014). "We detected both PTK6 mRNA and protein expression in all of breast cancer cells lines that we examined, as well as in the nontransformed MCF-10A human mammary gland epithelial cell line." (PMID 25153721, 2014). "Protein tyrosine kinase 6 (PTK6), also known as breast tumor kinase (Brk), is a non-receptor tyrosine kinase overexpressed in almost all type of breast cancers." (PMID 22792362, 2012). "In conclusion, in this study, we show that PTK6 protein expression in 426 breast cancer cases is of high prognostic value, independent of the classical morphological and molecular markers, such as lymph node involvement, tumour size, and HER2 status." (PMID 18781181, 2008). "We demonstrate that PTK6 is a prognostic marker of metastases-free survival in breast cancer, and is independent of the classical morphological and molecular markers of lymph node involvement, tumour size, and HER2 status." (PMID 17299391, 2007). "Expression of PTK6 in conjunction with that of the HER receptors has not previously been analysed in breast cancer tissue." (PMID 17299391, 2007).
breast carcinoma (continued). "Breast tumor kinase (Brk), also known as protein tyrosine kinase 6, is a nonreceptor tyrosine kinase expressed in more than 60% of breast cancers." (PMID 17997837, 2007). "Interestingly, in contrast to our studies, there was no observed effect of PTK6 shRNA expression on baseline levels of phospho-p38 in the breast cancer cells (T47D) used in these studies." (PMID 29167821, 2017). "However, despite growth inhibition of MDA-MB-231 breast cancer cells, the direct inhibition of PTK6 could not be demonstrated, and off-target effects were evident." (PMID 37509364, 2023). "Finally, we show that p38 MAPK activation is critical for PTK6 downregulation-induced apoptosis, a mechanism that we previously reported for survival of HER2+ breast cancer cells, highlighting conserved mechanisms of survival regulation by PTK6 across breast cancer subtypes." (PMID 29167821, 2017). "Although the role of PTK6 in breast cancer development and prognosis is not known, these results are of important clinical relevance as PTK6 may be a potential future target for the development of novel treatments for breast cancer." (PMID 18781181, 2008). "BReast tumor Kinase (BRK, also known as PTK6) is a non-receptor tyrosine kinase that is highly expressed in breast carcinomas while having low expression in the normal mammary gland, which hints at the oncogenic nature of this kinase in breast cancer." (PMID 33391524, 2021). "Downregulation of Protein tyrosine kinase 6 (PTK6), a non-receptor tyrosine kinase highly expressed in HER2+ breast cancer, led to p38 activation, Bim induction and apoptosis of Lapatinib-resistant HER2+ breast cancer cells." (PMID 26405162, 2015). "The cytoplasmic non-receptor tyrosine kinase (BRK, PTK6), originally cloned from a human metastatic breast tumour, shows elevated expression in breast carcinoma cell lines and in approximately two-thirds of primary breast tumours." (PMID 17299391, 2007).
prostate carcinoma (27 papers, 2011 to 2025). A carcinoma that arises from epithelial cells of the prostate gland. "In prostate cancer, increased PTK6 expression is associated with poor patient prognosis and recurrence." (PMID 38573548, 2024). "PTK6 is localized to the cytoplasm of PC3 cells and this cell line provides a model for assessing the mechanisms underlying altered PTK6 intracellular localization in prostate cancer." (PMID 21479203, 2011). "In addition, overexpression of PTK6 in prostate cancer cells causes re-localization to the nucleus from the cytoplasm." (PMID 37509364, 2023). "In addition, increasing levels of ALT-PTK6 are associated with decreased phosphorylation of PTK6 and enhanced nuclear function of PTK6 in prostate cancer." (PMID 37509364, 2023). "Our data indicate that combination therapies incorporating inhibition of PTK6 signaling may have added benefits in the treatment of PTEN-deficient prostate cancers." (PMID 29142193, 2017). "In addition, Grasso and colleagues also examined gene copy number alterations in 61 prostate cancer patients, and gain of PTK6 copy number correlated with loss of PTEN in 13/14 samples." (PMID 29142193, 2017). "Inhibition of PTK6 signaling in prostate cancers with loss of PTEN could provide therapeutic benefits and merits further investigation." (PMID 29142193, 2017). "Activation of PTK6 could mediate the PTEN loss to promote invasive prostate cancer." (PMID 38573548, 2024). "In addition to loss of PTK6 nuclear localization and activation at the plasma membrane, increased expression also may contribute to the development of prostate cancer." (PMID 29142193, 2017). "However, prostate cancer cells express higher levels of the transcript encoding full length PTK6." (PMID 21479203, 2011). "PTK6 is highly expressed in many tumor types, including lung, breast, ovarian and prostate cancers, as well as in about 70% of TNBC." (PMID 37932734, 2023). "According to previous studies, PTK6 can be used as an autophagy-related gene to evaluate the prognosis of patients with tumors, including glioma, prostate cancer, and pancreatic cancer." (PMID 36690663, 2023). "Co-expression and altered localization of ALT-PTK6 and full-length PTK6 have been detected in human colon and prostate cancer cell lines." (PMID 37509364, 2023). "This study revealed that ALT-PTK6 has a functional role in PTK6 signalling in prostate cancer by negatively regulating PTK6 activity and subcellular localization." (PMID 37509364, 2023). "Vemurafenib (PLX4032) inhibits PTK6 in both prostate and colon cancer cells and was able to reduce tumor growth in prostate cancer xenograft models." (PMID 37509364, 2023). "We chose several prostate cell lines, because the roles of PTK6 in prostate cancer have been extensively studied by our group, and we have shown that PTK6 regulates prostate cancer cell survival and metastasis and prostate tumor formation in vivo." (PMID 36228719, 2022). "Loss of tumor suppressor PTEN, a frequent event in prostate cancer, contributes to PTK6 activation; PTEN dephosphorylates PTK6 on Tyr342 and inhibits its activity." (PMID 36228719, 2022). "PTEN inhibits protein tyrosine kinase 6 (PTK6/BRK/Sik) activity in prostate cancer cells by dephosphorylating PTK6 at tyrosine 342 (PY342)." (PMID 35954330, 2022). "To explore PTK6-SRC crosstalk in prostate cancer, we examined colocalization of active PTK6 with active SRC in samples of transurethral resection of the prostate from patients who were diagnosed with CRPC." (PMID 36228719, 2022). "PTK6 antagonists can inhibit metastasis in triple-negative breast cancer and PTK6 activation can promote epithelial-to-mesenchymal transition in prostate cancer." (PMID 33109128, 2020). "Knockdown of cytoplasmic PTK6 in prostate cancer PC3 cells limits cell proliferation, migration, and anoikis resistance." (PMID 31278310, 2019). "Mechanistically, miR-214 inhibited prostate cancer cell proliferation by targeting protein tyrosine kinase 6 (PTK6)." (PMID 31278310, 2019).
prostate carcinoma (continued). "We also examined RNA expression from a cohort of prostate cancer patient samples in the Grasso data set available on Oncomine49, and found that loss of PTEN expression also coincides with an increase in PTK6 messenger RNA (mRNA)." (PMID 29142193, 2017). "In this study, the authors show that PTEN can act as a protein phosphatase that targets active PTK6, thereby regulating its oncogenic signaling in prostate cancer progression." (PMID 29142193, 2017). "Since we detected striking activation of PTK6 in a mouse model of prostate cancer, we aimed to better understand the clinical significance of PTK6 activation in prostate cancer patients." (PMID 29142193, 2017). "The same authors evidenced an higher expression of PTK6 in metastatic human prostate cancer samples, suggesting an oncogenic role for PTK6 in prostate tumor development and metastasis." (PMID 27713912, 2016). "PTK6 is expressed in normal prostate epithelial cells where it is largely localized to the nuclei, but in prostate cancers PTK6 nuclear localization is lost." (PMID 25153721, 2014). "If protein levels are representative, this suggests an additional mode of aberrant PTK6 function in prostate cancer, along with upregulation and mislocalization." (PMID 21479203, 2011). "While PTK6 is expressed in normal prostate, the intracellular localization of PTK6 changes in prostate cancers; it is nuclear in normal prostate epithelial cells, but relocalizes to the cytoplasm in prostate cancer." (PMID 21479203, 2011). "In human prostate cancer, increased expression of PTK6, its relocation from the nucleus to the cytoplasm, and subsequent activation at the plasma membrane facilitate the phosphorylation and activation of substrates like AKT, p130CAS, and FAK, thereby fostering cancer advancement." (PMID 40809015, 2025). "In a study of prostate cancer, activation of PTK6 in the plasma membrane was found to increase phosphorylation and to activate AKT,p130Cas and FAK, thereby promoting cancer cell proliferation, survival, migration, and epithelial-mesenchymal cell transformation." (PMID 37932734, 2023). "Similarly, in vitro studies on prostate cancer demonstrate that PTK6 is also dephosphorylated at Y342 by the phosphatase and tensin homolog (PTEN)." (PMID 37509364, 2023). "In prostate cancer, active PTK6 and active SRC colocalize within the same cells." (PMID 36228719, 2022). "PTK6 activation at the plasma membrane has been reported in breast and prostate cancer." (PMID 36228719, 2022). "In mouse models of breast and prostate cancer, disruption of Ptk6 impairs tumorigenesis." (PMID 36228719, 2022). "In prostate cancer, PTK6 activity negatively correlates with PTEN expression." (PMID 36228719, 2022). "PTK6 gene was also discovered to be amplified in prostate cancer." (PMID 33391524, 2021). "Indeed, the overexpression of PTK6 in prostate cancer cells promoted EMT via AKT activation, enhanced cell migration as well as metastasis in a prostate xenograft model." (PMID 34884984, 2021). "In prostate cancer, PTK6 contributes to increased phosphorylation and activation of its substrates, such as AKT serine/threonine kinase 1 (AKT), CAS scaffolding protein family member 1 (p130CAS), and focal adhesion kinase (FAK), thereby promoting the tumor progression." (PMID 31447885, 2019). "Targeting PTK6 to the plasma membrane by addition of a palmitoylation/myristoylation signal promoted the epithelial mesenchymal transition and enhanced growth and metastasis of prostate cancer xenograft tumors." (PMID 25153721, 2014). "In human and mouse prostate cancer cells, PTK6 is activated at the cell plasma membrane." (PMID 25153721, 2014). "Interesting, it is reported that PTK6 is located in the nuclei of normal prostate epithelium and well-differentiated prostate tumor, but it is located in the cytosol of poorly differentiated prostate carcinoma." (PMID 23758975, 2013).